CRP (C-reactive protein)
Diseases named in the same sentence as CRP in open-access papers (continued):
Sharing a sentence is not in itself a finding about the gene and the disease.
Myalgia (76 papers, 2012 to 2025). "Colocalization analysis also revealed significant evidence of a shared causal variant between polymyalgia rheumatica and CRP levels in the IL6 locus (PP.H4 = 0.85)." (PMID 40858837, 2025). "The risk factors for death included dyspnoea, muscle ache, elevated myocardial enzymes, elevated C3 in over-70 patients and dyspnoea, pharyngalgia, chronic cardiac disease, increased C-reactive protein, IgA, decreased platelets in under-70 patients." (PMID 33106442, 2020). "The risk factors for death included dyspnoea, muscle ache, elevated myocardial enzymes, elevated C3 in over-70 patients and dyspnoea, pharyngalgia, chronic cardiac disease, increased CRP, IgA, decreased platelets in under-70 patients." (PMID 33106442, 2020). "In summary, male sex, any coexisting disease, symptoms of cough, muscle ache, and diarrhea, laboratory abnormalities of decreased lymphocyte/albumin and increased CRP level are risk factors for severe/critical COVID‐19." (PMID 32397011, 2020). "In multivariate analysis, the evidence of these clinical features was significantly associated with CRP ≥ 68.7 mg/L, pericarditis (OR 1.316, 95% CI 1.125–1.800, p = 0.015) and myalgia (OR 3.100, 95% CI 1.439–6.681, p = 0.004)." (PMID 32645077, 2020). "A multiple linear regression analysis exhibited that fever (β coefficient (95% confidence interval) 2.1 (1.5–2.6)), myalgia (2.5 (2.0–3.1)), massive hemoptysis/alveolar hemorrhage (1.3 (0.4–2.2)), and mononeuritis multiplex (1.2 (0.5–2.0)) independently associated with CRP levels." (PMID 33664381, 2021). "Patients presenting fever, constitutional symptoms, polymyalgia rheumatica, high CRP and ESR levels, and low hemoglobin had a reduced risk of both visual and cerebrovascular complications, whether these complications are studied as a combined endpoint, or whether only CIE are studied." (PMID 37420252, 2023). "Of the pooled patients, 183/254 (72%) patients presented with constitutional symptoms, 159/212 (75%) with headache and 98/313 (31%) with polymyalgia rheumatica and the median CRP was 27 mg/L [interquartile range (IQR) 24.1–84.3]." (PMID 41323363, 2025). "They typically appear with systemic inflammation (high-grade fever and elevated C-reactive protein (CRP) and erythrocyte sedimentation rate (ESR)) in addition to significant myalgia associated with weakness in the afflicted muscle groups." (PMID 41497952, 2025). "Age, C-reactive protein, and involved joint distribution were factors leading to ultrasound complementation at the time of polymyalgia rheumatica diagnosis." (PMID 39545229, 2024). "Generally, patients with positive MPO-ANCA have a more active disease with higher CRP levels, higher ratios of fever and myalgia, and significantly more common rhinosinusitis than those with negative MPO-ANCA." (PMID 37215720, 2023). "Polymyalgia rheumatica is a common inflammatory rheumatic disease characterized by a high sedimentation rate, high C-reactive protein (CRP) levels, pain, and stiffness in the muscles of the shoulder and hip girdle." (PMID 38813491, 2023). "The results demonstrated that fever, distribution of peak temperature (>38°C), myalgia or arthralgia and distribution of CRP (≥10 per L) were significantly predictive factors." (PMID 33052140, 2020). "The most common clinical features were fever, cough, and myalgia with prevalence ranging from 30 to 97%, while lymphocytopenia and C-reactive protein were the most common abnormal laboratory findings (55–100%)." (PMID 32887660, 2020). "His physical examination was normal, but each episode of fever and myalgia was accompanied by high C-reactive protein (CRP) blood levels, while liver enzyme concentrations remained normal." (PMID 32498706, 2020). "Hematochemical analyses demonstrated slightly elevated serum levels of CPK (198 IU/L), lactate dehydrogenase (LDH, 304 IU/L), and CRP (13.8 mg/L), consistent with the developed myalgia and skeletomuscular damage." (PMID 26861356, 2016).
Myalgia (continued). "IL-6, CXCL-10/IP-10, CRP and presence of knee pain and myalgia were found to significantly predict persistence of post CHIKV musculoskeletal pain." (PMID 25343623, 2014). "Together with an urgent blood test (full blood count, CRP and erythrocyte sedimentation rate), other typical symptoms of GCA, such as headache, scalp tenderness, jaw claudication, weight loss and existing polymyalgia rheumatica, can be helpful indicators." (PMID 38674172, 2024). "Moreover, old data consider a CRP concentration of more than 6 mg/L as an additional criterion for the diagnosis of polymyalgia rheumatica." (PMID 37873776, 2023). "Furthermore, levels of CRP more than 68.7 mg/L predicted some clinical manifestations, including pericarditis and myalgia." (PMID 32645077, 2020). "Initially, these episodes responded well to anti-inflammatory drugs with defervescence, normalization of C-reactive protein (CRP) values and thrombocyte counts, as well as complete regression of lymphadenopathy and myalgia, and therefore were interpreted as inflammatory reactions to viral pathogens." (PMID 28959691, 2017). "However, patients with epidemic myalgia have normal or slightly elevated CRP and CK, and the pain typically lasts 1 to 4 days, although pain lasting as long as 45 days has been described." (PMID 27491355, 2016). "In the presence of arthralgia/myalgia specific laboratory tests could include: full blood count, C-reactive protein, erythrocyte sedimentation rate, ferritin, uric acid levels, liver profile, renal profile, serum protein electrophoresis, muscle enzymes, rheumatoid factor, antinuclear antibodies." (PMID 37151592, 2023). "Polymyalgia rheumatica (PMR) is a common disorder in patients over 50 years of age presenting with pain in proximal joints associated with morning stiffness along with elevated inflammatory markers erythrocyte sedimentation rate (ESR) and/or C-reactive protein (CRP)." (PMID 37091488, 2023). "Our inpatient univariable models identified higher eosinophil count, higher serum protein, lower age, lower CRP concentration, non-White racial identification, and rash as predictors of coccidioidomycosis, but muscle aches and immunocompromised status were negatively associated with disease." (PMID 35608552, 2022). "A diagnosis of polymyalgia rheumatica (PMR) was initially made according to the EULAR/ACR provisional classification criteria for PMR; however, due to C-reactive protein negativity, the diagnosis was established based on symptoms." (PMID 38516555, 2024). "In our study, the patients with positive MPO-ANCA suffered more fever and myalgia and had higher ESR, CRP, and BVAS, suggesting MPO-ANCA as an inflammatory mediator." (PMID 35833130, 2022). "Clinical remission was defined as the absence of clinical signs and symptoms in cranial and large vessel areas, polymyalgia rheumatica (PMR), and elevation of C-reactive protein (CRP) levels." (PMID 32264967, 2020). "One of these scans was performed in a patient with a history of GCA complicated by active polymyalgia rheumatica (PMR), with a persistently elevated CRP level despite treatment with high dose steroids." (PMID 33077771, 2020). "The possibility that polymyalgia rheumatica (PMR) can be diagnosed when both ESR and CRP are normal at the time of diagnosis and before therapy with glucocorticoids, has been often discussed in the literature." (PMID 30241359, 2018). "CRP was significantly higher in patients with these symptoms, while chemokines CCL2 (MCP-1), CCL3 (MIP-1α) and CXCL8 (IL-8) were higher in patients with rigors and myalgia." (PMID 41027884, 2025). "Arthralgia affecting the scapular and pelvic girdles in association with a severe morning stiffness and elevated C-Reactive Protein (CRP) and/or Erythrocyte Sedimentation Rate (ESR) could orientate toward a diagnosis of Polymyalgia Rheumatica (PMR)." (PMID 32283744, 2020).
Myalgia (continued). "The suspicion for LVV was based on increased laboratory inflammation parameters (CRP, ESR) and a variety of several non-specific symptoms, such as fatigue, night sweats, weight loss, malaise, fatigue, and myalgia." (PMID 23316356, 2012). "Polymyalgia rheumatica (PMR) is a common inflammatory condition primarily affecting middle-aged and older individuals, characterized by proximal limb pain, morning stiffness, and elevated inflammatory markers such as C-reactive protein (CRP) and erythrocyte sedimentation rate (ESR)." (PMID 40895860, 2025). "Among 152 patients with polymyalgia rheumatica, the flare, methotrexate add-on, and C-reactive protein normalization rates were 15.9 (95% confidence interval, 8.8-23.1)/100 person-years, 9.3 (3.6-15.0) /100 person-years, and 70.3 (61.3-79.2) /100 person-months, respectively." (PMID 39545229, 2024). "Second, the TAB-positive patients were older, with a “cranial form” of the disease (cephalic and ophthalmological symptoms) and a lower CRP level, as opposed to a “systemic form” (or large-vessel vasculitis form) with constitutional signs, polymyalgia rheumatica, and cough." (PMID 35683507, 2022). "In this study, we evaluated the activity of the neuroendocrine axes in patients with polymyalgia rheumatica (PMR) before and after tumor necrosis factor (TNF)-α-blocking etanercept treatment, which previously has been shown to reduce interleukin 6 (IL-6) and C-reactive protein (CRP) markedly in PMR." (PMID 22894827, 2012). "Typical clinical features may include fever, headache, jaw claudication, palpable and tender temporal arteries, symptoms of polymyalgia rheumatica (PMR), visual disturbance, and raised serologic inflammatory markers such as the erythrocyte sedimentation rate (ESR) or C-reactive protein (CRP)." (PMID 22811725, 2012). "In contrast, the results of meta-analysis showed that pulmonary comorbidities, PR3-ANCA positivity, use of plasma exchange, myalgia, DAH, CRP, Cr, rash, peripheral neuropathy, and hematuria did not correlate with AAV-ILD (p > 0.05)." (PMID 41197332, 2025).
Pancytopenia (76 papers, 2009 to 2026). An abnormal reduction in numbers of all blood cell types (red blood cells, white blood cells, and platelets). "Patients with pancytopenia are at risk of severe opportunistic infections, therefore, they should have monitored inflammatory parameters such as C-reactive protein (CRP), procalcitonin (PCT) and interleukin 6 (IL-6)." (PMID 38882583, 2024). "The diagnosis is often difficult, due to non-specific signs, symptoms and laboratory features, including fever, dyspnea, fatigue, weight loss, pancytopenia, and elevation of C-reactive protein (CRP), transaminases and creatinine." (PMID 36494813, 2022). "Upon hospitalization (Day +0), the patient presented pancytopenia, predominantly of platelets and leukocytes, low hemoglobin, and elevated CRP, creatinine, and transaminases." (PMID 40733580, 2025). "Laboratory tests revealed pancytopenia (white blood cell count, 300/μL; red blood cell count, 206 × 104/μL; platelet count, 5.0 × 104/μL), elevated C-reactive protein (CRP), and liver and kidney dysfunction, whereas tumor markers were within normal range." (PMID 41523456, 2025). "Her admission labs also revealed pancytopenia and elevation in both her sedimentation rate and C-reactive protein (CRP)." (PMID 40443627, 2025). "Hemophagocytic variant (HV) patients showed worse performance status, universal B symptoms, more bone marrow infiltration, higher mortality, pancytopenia, elevated inflammatory markers (CRP, LDH, ferritin), hypoglobulinemia and hypogammaglobulinemia." (PMID 41487580, 2025). "Initial hematological evaluation revealed marked pancytopenia, along with elevated erythrocyte sedimentation rate and C-reactive protein levels." (PMID 39820409, 2025). "Pancytopenia was aggravated (hemoglobin 9.1 g/dL [14–17.5 g/dL], leucocytes 1.79 × 103/μL [4–10 × 103/μL], thrombocytes 43 × 103/μL [140–450 × 103/μL]), and CRP (13.2 mg/dL [<0.5 mg/dL]), and procalcitonin (0.58 ng/mL [<0.5 ng/mL]) was elevated." (PMID 40559191, 2025). "The possibility of scrub typhus-associated HLH should be considered in patients presenting unidentifiable fever, significantly increased levels of CRP, pancytopenia, and especially those with suspected exposure history." (PMID 38784570, 2024). "Laboratory investigations demonstrated pancytopenia accompanied by spherocytosis on the peripheral blood smear, along with elevated C-reactive protein (CRP) levels." (PMID 39184709, 2024). "Her blood profile revealed pancytopenia, elevated C-reactive protein, and a deranged coagulation profile." (PMID 37525775, 2023). "The patient presented fever, dizziness, and myalgia, and laboratory results showed pancytopenia and increased CRP, AST, ALT, LDH, and BUN." (PMID 37267407, 2023). "On day 2, the blood tests showed pancytopenia and progression of the hyperinflammatory state (ferritin 6,870 μg/L and C-reactive protein 55 mg/L)." (PMID 36225555, 2022). "Due to moderately increased CRP (27.7 mg/L (<5)) and pancytopenia (leucocytes 0.9/nL, hemoglobin 9.6 g/dL, and thrombocytes 49/nL), an antibiotic treatment alongside stimulation with G-CSF had been initiated in the transferring hospital." (PMID 35448162, 2022). "Key findings included elevated CRP level, refractory shock, pancytopenia, splenomegaly, and lactic acidosis." (PMID 35414928, 2022). "Patient SAID5 (female, 12 years) presented with scleroderma/lupus like disease (facial features, skin thickness), accompanied with fever, livedoid rash, impressive lymphadenopathy, pleuritis, pancytopenia, increased CRP>200 mg/l (nv <5)." (PMID 35211430, 2022). "The patient exhibited pancytopenia, elevated CRP and ESR, hyperhomocysteinemia, mild hypoproteinemia (5.45 g/dL), and proteinuria (28.26 mg/dL)." (PMID 34941099, 2021). "Recurrent symptoms of high-grade fever, abdominal discomfort, pancytopenia, and high C-reactive protein level occurred for 16 months." (PMID 34889256, 2021).
Pancytopenia (continued). "Laboratory results indicated pancytopenia (leukocyte count:1.37×109/L, lymphocytes count: 1.17×109/L, hemoglobin: 42g/L, and platelet count: 25×109/L), high levels of C-reactive protein(69.6 mg/dL), and lactate dehydrogenase (2,280 U/L)." (PMID 32638943, 2021). "Laboratory data revealed pancytopenia, a further increase in CRP, a hemoglobin level of only 6.6 g/dL and elevated LDH." (PMID 32601727, 2020). "The abdominal pain resolved quickly, and she developed a mild fever with elevated CRP and pancytopenia in the 3rd week of treatment." (PMID 32211319, 2020). "Investigations showed pancytopenia, positive anti-nuclear factor and double-stranded DNA, high erythrocyte sedimentation rate with normal C-reactive protein levels and hypocomplementemia." (PMID 28932375, 2017). "Abnormal laboratory findings include pancytopenia, elevated liver function tests, raised C-reactive protein and interleukin-6 (IL-6), and hypergammaglobulinemia." (PMID 21615962, 2011). "Abnormal laboratory findings include pancytopenia, abnormal function of liver and kidney, raised CRP, IL-6 and hypergammaglobulinemia." (PMID 19400935, 2009). "This experience reaffirms the importance of considering HLH associated with specific pathogen infections in patients presenting with unexplained fever, significantly elevated CRP levels, and pancytopenia, particularly when there is a history of potential exposure." (PMID 41560107, 2026). "The initial laboratory findings included pancytopenia (hemoglobin 8.1 g/dL, leucocytes 2.05 × 103/μL, and thrombocytes 101 × 103/μL), including lymphopenia (11.1%), signs of inflammation (CRP 3.2 mg/dL), elevated serum creatinine (1.22 mg/dL), and bilirubin (1.6 mg/dL)." (PMID 40559191, 2025). "Laboratory workup showed pancytopenia, elevated C-reactive protein (CRP), and glomerulonephritis." (PMID 40129759, 2025). "Labs showed pancytopenia, elevated LFTs, and a normal C-reactive protein (CRP)." (PMID 40559715, 2025). "The CRP improved rapidly, but the pancytopenia persisted despite administration of filgrastim." (PMID 41523456, 2025). "The analysis reveals pancytopenia and elevated C-reactive protein." (PMID 39737108, 2024). "Laboratory findings indicated severe pancytopenia, neutrophil count of 109/μL, hemoglobin level of 7.7 g/dL, and platelet count of 15,000/μL, with a highly elevated inflammatory response with a C-reactive protein (CRP) level of 27.34 mg/dL." (PMID 38916715, 2024). "In conclusion, in addition to the known laboratory manifestations of hypersplenism such as severe pancytopenia, our results show some significant “beneficial” laboratory findings including lower HbS, CRP, and D-dimmer values and lower morphological and metabolic pathological properties of the RBCs." (PMID 36105295, 2022). "His laboratory showed pancytopenia and CRP elevation (20 mg/dL (<0.5))." (PMID 35448162, 2022). "The patient exhibited pancytopenia and elevated CRP and ESR." (PMID 34941099, 2021). "Initial laboratory results revealed pancytopenia, hypergammaglobulinemia, and elevated inflammatory markers (erythrocyte sedimentation rate (ESR) >100 mm/hr, C-reactive protein (CRP) 137.7 mg/L), raising suspicion for multiple myeloma." (PMID 40969728, 2025). "Laboratory testing revealed pancytopenia (white blood cell [WBC] count, 0.7 × 109/L; hemoglobin [Hgb], 46 g/L; platelet count, 47 × 109/L) and remarkably high C-reactive protein (CRP, 91.88 mg/L)." (PMID 41030452, 2025). "Labs on admission were remarkable for pancytopenia and elevated inflammatory markers, an elevated lactate dehydrogenase (LDH), ESR, C-reactive protein (CRP), and ferritin." (PMID 40041629, 2025). "The LASSO combined with 5-fold cross-validation identified 13 significant features from the candidate variables, as follows: maximum temperature, duration of fever, serum sodium, TG, HDL, LDH, ferritin, CRP, FIB, PT, TNF-α, pancytopenia, and liver damage." (PMID 38725078, 2024).